LINC02624 (long independently transcribed non-coding RNA 2624)
Gene: Long non-coding RNA gene on chromosome 10 (106,140,143 to 106,188,722, forward strand). Ensembl gene ENSG00000229775.
Diseases named in the same sentence as LINC02624 in open-access papers:
LINC02624 is named in the same sentence as 2 diseases in open-access papers, as found by Europe PMC text mining. Sharing a sentence is not in itself a finding about the gene and the disease.
LINC02624 shares sentences with these, for which no sentence is quoted: fibroids (2 papers); tumor (1).